ADSL (adenylosuccinate lyase)
Description:
Catalyzes two non-sequential steps in de novo AMP synthesis: converts (S)-2-(5-amino-1-(5-phospho-D-ribosyl)imidazole-4-carboxamido)succinate (SAICAR) to fumarate plus 5-amino-1-(5-phospho-D-ribosyl)imidazole-4-carboxamide, and thereby also contributes to de novo IMP synthesis, and converts succinyladenosine monophosphate (SAMP) to AMP and fumarate.
Synonyms: ASL; ASase; AMPS
Tractability: Small molecule: a structure with a bound ligand is known; it has a high-quality binding pocket. PROTAC: UniProt records ubiquitination sites on it; ubiquitination databases record sites on it; its protein half-life has been measured.
Target class: Enzyme; Lyase
Gene: Protein-coding gene on chromosome 22 (40,346,461 to 40,390,463, forward strand). Ensembl gene ENSG00000239900.
Subcellular location (Human Protein Atlas): Cytosol
Pathways (Reactome):
Metabolism: Purine ribonucleoside monophosphate biosynthesis
Gene Ontology:
Molecular function: (S)-2-(5-amino-1-(5-phospho-D-ribosyl)imidazole-4-carboxamido) succinate lyase (fumarate-forming) activity; identical protein binding; N6-(1,2-dicarboxyethyl)AMP AMP-lyase (fumarate-forming) activity; catalytic activity
Biological process: AMP biosynthetic process; 'de novo' AMP biosynthetic process; purine nucleotide biosynthetic process; 'de novo' IMP biosynthetic process; 'de novo' XMP biosynthetic process; aerobic respiration; AMP salvage; GMP biosynthetic process; purine ribonucleotide biosynthetic process; response to hypoxia; response to muscle activity; response to nutrient; response to starvation
Cellular component: cytosol; protein-containing complex
Genetic constraint (gnomAD): Loss-of-function variants: 41 observed, 58.14 expected, observed/expected ratio (o/e) 0.71, 90% interval 0.55 to 0.92. The upper end of that interval is the gene's LOEUF score, 0.92, which puts it in group 3 of 6, group 1 being the genes least tolerant of losing a copy. Missense variants: 510 observed, 633.64 expected, observed/expected ratio (o/e) 0.8, 90% interval 0.75 to 0.87. Synonymous variants: 191 observed, 224.65 expected, observed/expected ratio (o/e) 0.85, 90% interval 0.75 to 0.96.
Gene-disease validity (ClinGen):
ClinGen rates the evidence that ADSL causes each of these diseases.
adenylosuccinate lyase deficiency (autosomal recessive): Definitive. Adenylosuccinate lyase deficiency (ADSL deficiency) is a disorder of purine metabolism characterized by intellectual disability, psychomotor delay and/or regression, seizures, and autistic features.
Homologues: Orthologues: macaque ADSL (99% identical), chimpanzee ADSL (97% identical), mouse Adsl (94% identical), dog ADSL (94% identical), rat Adsl (93% identical), guinea pig ADSL (92% identical), pig ADSL (89% identical), rabbit ADSL (88% identical), tropical clawed frog adsl (82% identical), zebrafish adsl (76% identical), Drosophila melanogaster Adsl (66% identical), Caenorhabditis elegans adsl-1 (45% identical). Paralogues in human: ASL (21% identical), FH (19% identical).
Diseases named in the same sentence as ADSL in open-access papers:
ADSL is named in the same sentence as 77 diseases in open-access papers, as found by Europe PMC text mining. Sharing a sentence is not in itself a finding about the gene and the disease. The quoted sentences say what the papers report.
prostate carcinoma (6 papers, 2021 to 2025). A carcinoma that arises from epithelial cells of the prostate gland. "Recent studies have shown that ADSL promotes the development of prostate cancer by regulating the expression of cell cycle genes." (PMID 40313243, 2025). "Increased levels of ADSL have been observed in various conditions, including colorectal, breast, and prostate cancer." (PMID 38433141, 2024). "Studies have revealed that ADSL plays a role in prostate cancer progression by inhibiting the cell cycle pathway." (PMID 37976135, 2023). "ADSL, an essential enzyme for de novo purine biosynthesis, is thought to be a novel oncogene in prostate cancer and colorectal carcinoma." (PMID 37999212, 2023).
breast carcinoma (5 papers, 2019 to 2025). "Numerous genomic variants, also known as SNPs, including CYP1A2 (rs17861162) and ADSL (rs3788579), appear to be correlated with the risk of breast cancer development." (PMID 38433141, 2024). "This study explores the role of CYP1A2-rs17861162 and ADSL-rs3788579 SNPs in breast cancer risk among Iranian women." (PMID 38433141, 2024). "Additionally, in our investigation of the ADSL gene's SNP rs3788579, we found a significantly higher prevalence of the T allele in individuals with breast cancer compared to the healthy group, exceeding by 28.5% (P-value = 0.00)." (PMID 38433141, 2024). "It is notable that approximately 25% of these were breast cancer cell lines, further highlighting the importance of elucidating the role of ADSL in cancer development and progression." (PMID 38433141, 2024). "In ADSL-rs3788579 SNP, breast cancer patients had a significantly higher prevalence of the T allele, with a 28.5% increase compared to controls." (PMID 38433141, 2024). "This study highlights significant genetic alterations in CYP1A2-rs17861162 and ADSL-rs3788579 SNPs among breast cancer patients in North-West Iran, suggesting their potential as diagnostic and prognostic biomarkers." (PMID 38433141, 2024). "ADSL displayed the highest expression in TNBC compared with the other subtypes of breast cancer, i.e., Her2+, luminal (A and B), and normal-like." (PMID 31729379, 2019). "In a recently published study on “Project Drive”34, a genome-wide shRNA screening identified ADSL as essential for cancer cell proliferation in 40 different cell lines, of which almost 25% were breast cancer cell lines." (PMID 31729379, 2019). "Here we show that ADSL expression is significantly upregulated in TNBC patients compared with the other breast cancer subtypes and normal breast tissues." (PMID 31729379, 2019). "We did not observe the rescue of cMYC expression, suggesting that ADSL proline hydroxylation is critical for ADSL regulation of cMYC and breast cancer cell proliferation." (PMID 31729379, 2019). "In addition, ADSL expression was higher in triple negative breast cancer (TNBC) than in other breast cancer subtypes and normal breast tissues, and ADSL knockout inhibited the proliferation and invasion of TNBC cells both in vitro and in vivo." (PMID 40313243, 2025). "Our results suggest that ADSL proline 24 hydroxylation is important for regulating ADSL activity, which controls adenosine (and adenine) levels that regulate cMYC protein level, and leads to downstream metabolic changes and breast cancer cell proliferation." (PMID 31729379, 2019). "ADSL knockout by using two independent sgRNAs impaired breast cancer cell proliferation." (PMID 31729379, 2019). "ADSL expression is higher in TNBC than other breast cancer subtypes or normal breast tissues." (PMID 31729379, 2019). "Studies investigating the role of ADSL and CYP1A2 SNPs in the development and progression of breast cancer are rather limited." (PMID 38433141, 2024). "However, ADSL role in breast cancer, particularly TNBC, was completely unknown." (PMID 31729379, 2019). "When re-introduced in ADSL knockout cells, wild-type ADSL, but not the mutant missing the hydroxylation site (P24A), can rescue MIR22HG level, thus promoting oncogene cMYC expression and breast cancer cell growth." (PMID 31729379, 2019).
endometrial cancer (5 papers, 2019 to 2025). Primary or metastatic malignant neoplasm involving the endometrium (mucous membrane that lines the endometrial cavity). "It was previously shown that ADSL levels modulate Akt phosphorylation in endometrial cancer and that TCA cycle defects, specifically the accumulation of α-ketoglutarate (αKG), as well as ROS increase can activate the mTOR signaling pathway 7,50-53." (PMID 33754045, 2021). "Fumarate is a TCA cycle intermediate and a well-known oncometabolite which has been connected to ADSL oncogenicity in endometrial cancer." (PMID 33754045, 2021). "Only recently a study provided a potential molecular mechanism for ADSL in endometrial cancer oncogenesis, by increasing killer cell lectin-like receptor C3 expression through fumarate production." (PMID 31729379, 2019). "Furthermore, adenylosuccinate lyase (ADSL), an enzyme involved in de novo purine synthesis, has been shown to enhance the aggressiveness of endometrial cancer." (PMID 40552664, 2025). "Moreover, fumarate accumulation is linked with endometrial cancer aggressiveness, via adenylosuccinate lyase (ADSL) and killer cell lectin-like receptor C3 (KLRC3): the knock-down of ADSL decreases KLRC3 that in turn reduces cell proliferation, migration and invasion." (PMID 34065551, 2021).
triple-negative breast carcinoma (5 papers, 2019 to 2025). An invasive breast carcinoma which is negative for expression of estrogen receptor (ER), progesterone receptor (PR), and human epidermal growth factor receptor 2 (HER2). "Increased levels of ADSL have been observed in several cancer types 6-8 and have been shown to increase proliferation, migration, and invasive capability of endometrial and triple-negative breast cancer cell lines 6,7." (PMID 33754045, 2021). "By developing an enzyme-substrate trapping strategy coupled with TAP-TAG or orthogonal GST- purification followed by mass spectrometry, we identify adenylosuccinate lyase (ADSL) as an EglN2 hydroxylase substrate in triple negative breast cancer (TNBC)." (PMID 31729379, 2019). "By developing an optimized enzyme-substrate-trapping strategy coupled with TAP-TAG purification and mass spectrometry, here we identify adenylosuccinate lyase (ADSL) as a substrate of the hydroxylase EglN2 in triple negative breast cancer (TNBC)." (PMID 31729379, 2019). "Consequently, knocking out ADSL hampers the growth and invasion of triple-negative breast cancer (TNBC) cells, both in vitro and in vivo." (PMID 38433141, 2024). "Additionally, ADSL contributes to the development of triple-negative breast cancer by activating cMYC." (PMID 37976135, 2023). "We also observed a correlation between the expression levels of ADSL and the MYC oncogene, whose expression has been shown to be indirectly regulated by ADSL in triple-negative breast cancer 6 and whose upregulation of target genes is a signature of the CMS2 subtype 37." (PMID 33754045, 2021). "Notably, represses ADSL expression and inhibits the long noncoding RNA MIR22HG to regulate the proliferation and invasion of triple-negative breast cancer cells." (PMID 37976135, 2023). "Given that ADSL-overexpressing Caco-2 cells displayed a significant enrichment for MYC-targets and that ADSL was previously shown to activate the c-MYC pathway in triple negative breast cancer 6, we therefore asked whether a similar mechanism occurs in CRC." (PMID 33754045, 2021).
glioma (4 papers, 2020 to 2024). A benign or malignant brain and spinal cord tumor that arises from glial cells (astrocytes, oligodendrocytes, ependymal cells). "When we used univariate Cox's regression analysis, we found that ASL, ADSL, and FH were unfavorable factors for glioma patients, while SDHA was a favorable prognostic factor for patients." (PMID 37786553, 2023). "Besides, we also found that ASL, ADSL, and FH promote the malignant phenotype in glioma patients, while SDHA inhibits malignant progression." (PMID 37786553, 2023). "The gene expression levels of H6PD, G6PD, ADSL, APRT, GMPS, PRPS1, and IMPDH1 in human glioma patients were significantly higher than those in the control group." (PMID 33723244, 2021).
lung carcinoma (4 papers, 2021 to 2023). "In this study, we discovered for the first time that dysregulated purine metabolism contributes to the acquisition of the DTP state, regulated by the miR-21 guide and passenger strand repressing ADSL in EGFR-mutant lung cancer cells." (PMID 35840668, 2022). "Using a bioinformatic tool, Lung Cancer Explorer, we performed a correlation analysis between expression for precursor MIR21 and ADSL mRNA across 292 lung cancer patient tissues." (PMID 35840668, 2022). "Our western blot data has shown the increased expression of MUC1-CT and decreased expression of ADSL in lung cancer cell lines H1975 and H1650 than in a non-tumorigenic and immortalised lung epithelial cell line AALE, indicating a negative association between MUC1-CT and ADSL expression." (PMID 36810913, 2023). "Thus, our data first demonstrate silenced ADSL and reduced AICAR in the DTPCs in lung cancer." (PMID 35840668, 2022).
microcephaly (4 papers, 2017 to 2025). A congenital or acquired developmental disorder in which the circumference of the head is smaller than normal for the person's age and sex. "ADSL-deficient chicken and zebrafish embryos displayed impaired neurogenesis and microcephaly." (PMID 35133277, 2022). "Different amino acid changes around the site of an AMH-specific derived protein, ADSL (A429V), can bring about adenylosuccinate lyase deficiency (R426H; D430N), the symptoms of which include developmental delay, autistic-like traits, aggressiveness, and microcephaly." (PMID 29045412, 2017). "Most of the patients with adenylosuccinate lyase (ADSL) deficiency present with a severe form (type I) characterized by severe psychomotor retardation, early onset of seizures, and microcephaly." (PMID 41226098, 2025). "ADSL deficiency (ADSLD) causes numerous neurodevelopmental pathologies, including microcephaly and autism spectrum disorder." (PMID 35133277, 2022).
adenylosuccinate lyase deficiency (3 papers, 2021 to 2023). "Mutations in ADSL result in the rare autosomal recessive disorder adenylosuccinate lyase deficiency, while CCT2 mutations evoke the rare disease Leber congenital amaurosis." (PMID 37905813, 2023). "Adenylosuccinate lyase deficiency (ADSLD) is an ultrarare neurometabolic recessive disorder caused by loss-of-function mutations in the ADSL gene." (PMID 33648541, 2021).
autism (3 papers, 2017 to 2025). Persistent deficits in social interaction and communication and interaction as well as a markedly restricted repertoire of activity and interest as well as repetitive patterns of behavior. "ADSL deficiency leads to autism-related features, which have been consistently reported in studies on inborn errors of metabolism (IEM) associated with ASD." (PMID 36818658, 2023). "Adenylosuccinate lyase (ADSL) deficiency leads to a purely genetic form of autism by re-directing a large proportion of FOCM toward purine synthesis to compensate for a reduction in de novo purine synthesis." (PMID 28301476, 2017).
colorectal cancer (3 papers, 2021 to 2023). A primary or metastatic malignant neoplasm that affects the colon or rectum. "In conclusion, our investigation highlights the multifaceted role of ADSL as a new oncogene in colorectal cancers and strongly supports a role for ADSL overexpression in sensitizing tumor cells to 6-MP." (PMID 33754045, 2021). "In particular, we found that ADSL overexpression correlates with the expression of many genes coding for DNA polymerases and S-phase signaling checkpoints, many of which are part of a “DNA replication signature” found dysregulated in colorectal cancer." (PMID 33754045, 2021). "However, we note that essential genes may also act as functional drivers, as demonstrated for ADSL, a tumor-promoting effector in colorectal cancer." (PMID 34313788, 2021). "Here we sought to investigate the putative role of ADSL in colorectal carcinoma (CRC) carcinogenesis and response to antimetabolites." (PMID 33754045, 2021).
epilepsy (3 papers, 2015 to 2021). A brain disorder characterized by episodes of abnormally increased neuronal discharge resulting in transient episodes of sensory or motor neurological dysfunction, or psychic dysfunction. "ADSL deficiency is known to cause epilepsy or autistic features among other characteristics, and EP300 is known to play a role in Rubinstein-Taybi syndrome which includes features overlapping with PMS (e." (PMID 34228749, 2021). "In conclusion, using Trio-WES, we identified three novel mutations in ADSL gene and using molecular diagnosis, we refined the diagnosis from “Epilepsy” to “Adenylosuccinate Lyase Deficiency”." (PMID 28487569, 2017). "ADSL deficiency can cause onset of epilepsy in the first year of life." (PMID 25112391, 2015). "Approximately half of the patients with ADSL deficiency suffer from epilepsy, which is often intractable, but not always associated with status epilepticus." (PMID 25112391, 2015).
glioblastoma (3 papers, 2020 to 2025). The most malignant astrocytic tumor (WHO grade IV). "This study identified six PMRGs (SARDH, ACHE, ADSL, PNPLA3, MAPK1 and SREBF2) as potential prognostic biomarkers for glioblastoma." (PMID 40313243, 2025). "We show that the accumulation of AICAR in glioblastoma cells is due to impairment of the mechanisms involved in the conversion of AICAR to AMP upon ID1 knockout, as evidenced by the reduction in ADSL expression in ID-1−/− cells." (PMID 39455562, 2024). "Elevated expression of purine synthetic enzymes (PRPS1, ADSL, and GMPS) in metabolic subpathway 00230_5/00230_6 of the purine metabolic pathway is correlated with poor prognosis in glioblastoma patients." (PMID 33072547, 2020).
hepatocellular carcinoma (2 papers, 2022). A malignant tumor that arises from hepatocytes. "Depletion of ADSL in hepatocellular carcinoma upregulates activating transcription factor 4 (ATF4) and induces mitochondrial stress; however, the effect of SAICAR has not been examined." (PMID 36557247, 2022). "Furthermore, our results are supported by previous work that shows that genetic knockout of adenylosuccinate lyase (ADSL) impairs mitochondrial function in hepatocellular carcinoma, suggesting the importance of purines for mitochondrial function." (PMID 35453502, 2022).
Hyperglycemia (2 papers, 2014 to 2022). An increased concentration of glucose in the blood. "No hyperglycemia was reported in ADSL-deficient patients, and only transient hypoglycemia was described in ATIC-deficient patients that was associated with increased activation of the insulin pathway in hepatocytes." (PMID 35323684, 2022). "In addition to this, when ADSL was overexpressed in high fat diet induced obese mice, it resulted in reduced the fasting hyperglycemia (20% reduction), and increased glucose and pyruvate tolerance." (PMID 24855629, 2014).
Insulin resistance (2 papers, 2023 to 2025). Increased resistance towards insulin, that is, diminished effectiveness of insulin in reducing blood glucose levels. "Taken into conjunction with the downregulation of Dgat2, AdSL may also aid in TRF’s ability to combat insulin resistance under HFD conditions." (PMID 36810287, 2023). "In addition, ADSL overexpression activates AMPK and ameliorates insulin resistance in high-fat-diet-induced obese mice." (PMID 41471373, 2025).
Intellectual disability (2 papers, 2025). "Examples include SCN2A, IQSEC2, and ADSL, whose mutations are associated with seizures, motor delays, and severe intellectual disability." (PMID 41300846, 2025). "Given that ADSL deficiency is characterized by both elevated levels of S-Ado and intellectual disability, we explored whether common genetic variants associated with S-Ado levels are correlated with cognitive abilities." (PMID 40758872, 2025).